CD69 (CD69 molecule)
Diseases named in the same sentence as CD69 in open-access papers (continued):
Sharing a sentence is not in itself a finding about the gene and the disease.
influenza (continued). "Consistent with our previous report, γ-SFV failed to induce partial lymphocyte activation while both live influenza (A/PR8 and A/PC) and their γ-irradiated counterparts induced up-regulation of CD69 expression on CD3+ T cells." (PMID 21998693, 2011). "Congruently, in a murine influenza model, NK1.1- DN T cells localized in the lung parenchyma, exhibited a pre-activated TRM phenotype (CD44+CD69+CD103+), and expanded robustly after infection, underscoring the capacity of DN TRM to participate in acute, site-restricted immunity." (PMID 41164185, 2025). "Interestingly, we also found decreased percentage of CD69+ Tet+ influenza specific CD8+ T cells and CD69+ CD8+ T cells in alcohol consuming influenza infected mice in contrast to water-fed control mice." (PMID 37485352, 2023). "Therefore, significantly decreased expression of CD28, CD40L, IL12R, and CD69 in obese subjects leads to markedly lower activation of CD4+ and CD8+ T cells after influenza vaccination." (PMID 36295052, 2022). "The source of heterogeneity in CD69 expression in lung resident T cells observed in many studies after influenza infection has not yet been defined." (PMID 35215193, 2022). "For influenza-induced OT-I T cells, this marker was mostly expressed by the TRM CD69+ CD103+ cells." (PMID 33479479, 2021). "Furthermore, previous reports showed that MAIT cells rapidly acquire the expression of exhaustion markers such as CD38, CD69, PD-1, and TIM in patients with acute viral infection by dengue or influenza." (PMID 34659215, 2021). "A functional test to assess sensitization of T cells to vaccine antigens in order to estimate the effectiveness of memory T cells was performed by evaluating the expression of an activation surface marker (CD69) on CD4+ and CD8+ T cells following 24h incubation with the influenza vaccine antigens." (PMID 31600331, 2019). "However, only CTL memory induced by intranasal vaccination was protective against influenza viral challenge, and correlated with an enhancement of memory CTLs in the airways and CD103+ CD69+ CXCR3+ resident memory-like CTLs in the lungs." (PMID 27997610, 2016). "The origins and the differential functions of eosinophils with a phenotype characterized as CD69/CD125/CD63high and CD44/CCR3low could be subjects of further investigations, particularly in other viral respiratory diseases, such as influenza or respiratory syncytial virus infection." (PMID 40710346, 2025). "In addition, the frequency of CD69+ TEMRA cells also correlated with the duration of coughing, and a trend toward correlation with the symptom score despite lower frequency of TEMRA cells than KIR+RA+ T cells expressing CD69 at the time of influenza." (PMID 34043881, 2021). "When compared to healthy individuals not exposed to influenza antigens, percentages but not absolute numbers of NK cells expressing CD69 were higher in acutely infected subjects (p<0.0001), suggesting that most of the peripheral blood NK cells that do not home to other tissues express CD69." (PMID 21966414, 2011). "In humans, severe/lethal 2009 H1N1 influenza virus infection in 3 cases was associated with reduction of NK cells rather than effector CD8+ T cells, and influenza vaccination led to increased levels of NK cells with activation markers CD56 and CD69." (PMID 22761567, 2012). "The transient activation of CD69+ T cells, peaking at day 3, without sustained elevation of PD-1/CTLA-4, challenges the paradigm of “vaccine exhaustion” observed in frequent revaccination against influenza." (PMID 40746539, 2025). "Consistent with our hypothesis that early up-regulation of CD69 by T-cells was not influenza-specific, activated (CD69+) CD8+ influenza specific T-cells were detected only after day 9 post-infection." (PMID 19922665, 2009).
influenza (continued). "An example to prove this fact is that the overall frequency of influenza-specific CD8+ pulmonary memory T lymphocytes does not show variations with the donor’s age, while the subgroup of influenza-specific TRM lymphocytes with phenotype CD103+, CD69+ decreases with age." (PMID 35784300, 2022).
viral infection (53 papers, 2008 to 2025). "On the other hand, CD69-deficient mice enhances NK cell response to increase protection from viral infection." (PMID 35652109, 2022). "At the same time, high CD69 expression is associated with viral infections and is a promising therapeutic target that can improve immunosuppression in burn patients." (PMID 36518755, 2022). "Notably, increased expression of complement regulatory proteins (e.g. CD35, CD55, CD46, and CD69) on neutrophils and monocytes has been associated with bacterial and viral infections." (PMID 40568581, 2025). "Combined, these results indicate CD69+CD4+ T cells are a major early target for viral infection, and their rapid loss by direct infection may have profound effects on intestinal immune regulation in HIV infected patients." (PMID 22096538, 2011). "NK cells can recirculate from blood to tissues, where they can be quickly recruited during viral infection or tumor growth, and, as with other lymphocytes, their tissue retention is facilitated by CD69, CD103 (αE integrin), and CD49a expression." (PMID 40626357, 2025). "We found that viral infection substantially enhanced the frequency of the CD11b+ and CD69+ NK subsets." (PMID 37108306, 2023). "It is known that virus infection results in polyclonal activation of B cells, whose activation marker was the upregulation of the CD69+ B cell." (PMID 37559719, 2023). "CD69 was only found to exhibit a significant correlation with virus infection using BaL-mediated entry (p < 0.05 in 18/20 donors, mean R-square = 0.86), potentially highlighting a higher dependence of R5-tropic viruses to cells in early activation." (PMID 38067117, 2023). "Available evidence suggests that RBAC is a potent inducer of NKC cytotoxicity against aberrant cells due to viral infection and tumorigenesis, achieved through increased CD69 and CD25 surface markers." (PMID 37687141, 2023). "Resident memory T cell markers (CD44, CD62L, CD69 and CD11a) were also analysed to characterise the TRM population, previously associated with protection against viral infection." (PMID 33549390, 2021). "CD4+ T cell percentage was ~10-fold low compared to CD8+ T cells based on the evaluation of the early activation marker, CD69, together with HLA-DR (marker of cellular activation) after viral infection in both groups of individuals." (PMID 34571855, 2021). "With regard to CD69, it was reported that targeting CD69 enhanced the early control of virus infection which related to increased numbers of cytokine-producing T cells and NK cells in the periphery." (PMID 32849474, 2020). "Collectively, these data show that like naïve CD8+ T cells, circulating memory CD8+ T cells become CD69+ TRM primarily at the site of viral infection in an antigen-specific manner." (PMID 30875408, 2019). "Collectively, these findings demonstrate that TCM CD8+ T cells become cytolytic following rapid infiltration of the skin to protect against viral infection and subsequently differentiate into functional CD69+ tissue-residents." (PMID 30875408, 2019). "In contrast to naïve CD8+ T cells, most circulating TCM CD8+ T cells do not express CD103 in the skin microenvironment during the resolution of viral infection and only a subset ultimately became functional CD69+/CD103- TRM." (PMID 30875408, 2019). "On day15 post-infection, memory P14 CD8+ T cells had trafficked into the skin of both viral infections, but expressed more CD69 when cognate antigen was present in the VacV-infected skin microenvironment." (PMID 30875408, 2019). "In our previous study, we used a well‐established mouse model of MCMV brain infection to demonstrate a role for the PD‐1: PD‐L1 pathway in development of CD103+CD69+ CD8+ bTRM populations in vivo following acute viral infection." (PMID 29602245, 2018).
viral infection (continued). "Previous work from our laboratory has demonstrated in vivo persistence of CD103+CD69+ brain resident memory CD8+ T‐cells (bTRM) following viral infection, and that the PD‐1: PD‐L1 pathway promotes development of these TRM cells within the brain." (PMID 29602245, 2018). "At day 4 PI we observed that B cells (CD19+) from TLR3KO mice responded to viral infection by upregulating surface expression of the activation marker CD69 and the costimulatory molecule CD86 to levels comparable to that observed on B cells from WT NOD mice." (PMID 19122812, 2009). "The rapid systemic appearance of CD69 expression suggested that a soluble factor such as IFNα, a known early responder to viral infections and strong trigger of CD69 expression, was inducing the response." (PMID 19568424, 2009). "The proportion of CD4+ and CD8+ cells among CD69+ lymphocytes is shown 10 days after virus infection." (PMID 18335041, 2008). "We next tested if viral infections induce CD69 expression in the lung endothelium in mice." (PMID 40617350, 2025). "Similarly, another study suggests that upregulation of CD69, after yellow fever vaccination, can promote T cell migration and retention in the lymph nodes, the home for TCM." (PMID 36817441, 2023). "However, following HIV infection, approximately one third of infected cells expressed the activation marker CD69, suggesting upregulation due to viral infection." (PMID 34465136, 2022). "CD69 is highly upregulated in all immune cells in response to viral infection." (PMID 35652109, 2022). "Importantly, the increased durability of CD69+ CD103+ 4M CD8+ T cells at day 100 post-infection likely played an important role in their enhanced ability to control local virus infection." (PMID 34143731, 2021). "To test this hypothesis, we sorted CD4+ T cells from LCMV-infected mice on day 4 because it has been shown that CD69 expression levels are near their peak after virus infection in vivo." (PMID 29250063, 2017). "In contrast to HLA-DR+/CD38+ NK cells, there was a slow but significant decrease in CD69+ NK cells following cART initiation, consistent with CD69 being an early marker of cellular activation known to decline during the convalescent stage of viral infections such as Hantavirus." (PMID 28713370, 2017). "The induction of CD69 by METH at early time-point during viral infection might play an important role in regulation of the subsequent immune responses." (PMID 26322025, 2015). "Both serum-cultured and NBM-cultured primary GBM cells could activate T cells when treated with free NKG2D BiTE, but only serum-cultured primary GBM cells supported enough viral infection for a significant increase in CD69 activation marker to be detected when infected with G207-NKG2D BiTE virus." (PMID 38724464, 2024). "Moreover, in line with increased TCR signaling during chronic viral infection, we observed a conserved increase in the expression of AP-1 family members Jund and Junb, as well as in Cd69, Nr4a2, and Tox gene expression across all CD4+ T cell subsets during LCMV Cl13 infection." (PMID 36255051, 2022). "It was reported that primary viral infection might cause an IFN-I-dependent and systemic “partial” activation of T lymphocytes that was characterized by up-regulated expression of early activation marker CD69 and co-stimulatory molecule CD86." (PMID 32849474, 2020). "Because the previous experiment demonstrated that TCM became the CD69+ TRM that formed in the skin during secondary viral infection, we next tested whether TCM or naïve CD8+ T cells exhibited a greater capacity to express CD103 and/or differentiate into TRM following VacV infection." (PMID 30875408, 2019). "Additionally, CD69 has been used as an early immune marker for human viral infections and chronic inflammatory diseases; it could be expressed constitutively in monocytes, and their activation results in increases of reactive oxygen species." (PMID 25254368, 2014).
viral infection (continued). "Moreover, it was suggested that B cells expressing higher levels of CD69 played a role in viral latency and this role was not directly linked to viral infection of these cells since only a minority of CD69+ B cells were infected." (PMID 18931086, 2008). "To evaluate how viral infection modulates the activation status of unswitched memory B cells, we evaluated the expression of the CD86 and CD69 activation antigens as well as the CD21 co-receptor on total memory B cells (rather than antigen-specific B cells)." (PMID 37638016, 2023). "To assess the influence of viral infection on DN1 B cell activation, we evaluated expression of the CD69 and CD86 activation receptors on virally infected and control individuals." (PMID 36131937, 2022). "To determine how viral infection influenced the activation state of DN2 cells, we quantified levels of the CD69 and CD86 on this subset." (PMID 36131937, 2022). "Overall, it is clear that viral infection modulates the phenotype of the novel DN3 subset such that these cells have reduced BAFFR and CD86 but elevated levels of FcRL5, CD22, and CD69 during severe disease." (PMID 36131937, 2022). "On day 3 post viral infection, SMARTA CD4+ T cells of both genotypes showed similar upregulation of T-cell activation markers CD69 and CD44, and downregulation of CD62L." (PMID 33637761, 2021). "Studies in murine models of viral infection have demonstrated that significant proportions of TRM cells develop 2–3 weeks after infection, consistent with the time frame in which integrin+CD69+ cells developed within subcutaneous tumors in our model." (PMID 28018343, 2016). "During both acute and chronic viral infections, the frequency of MAIT cells in the peripheral blood decreases with an apparent enrichment in the airways, whereas the expression of HLA‐DR, PD‐1, CD38 and CD69 is upregulated." (PMID 39980239, 2025). "As expected, the frequency of CD69+, CD25+, GzmB+, and CD317+ cells significantly increased at 3DPI and 6DPI compared with PBS-treated mice, demonstrating cellular activation and the initiation of effector functions in response to viral infection." (PMID 38814732, 2024). "Activated monocytes highly express CD69, and activated monocytes have a higher viral load during virus infection than non-activated monocytes." (PMID 36518755, 2022). "In addition, C2 appeared to associate with positive regulation of inflammatory responses, as indicated by the high expression of Cd69 and the enrichment of IFN-γ signalling, toll-like receptor signalling and the pathways related to viral infections." (PMID 34858827, 2021). "Our data found that catechins ingestion increased the CD8+ T-cell percentage, upregulated CD25/CD69/CD94 expression in CD8+ T cells and mildly increased type I cytokines release to promote the adaptive immunity against viral infections, such as SARS-CoV or SARS-CoV-2." (PMID 34200327, 2021). "Collectively, these data suggest that circulating memory CD8+ T cells traffic directly into the skin in a CD62L-independent manner to provide protective immunity against viral infection, but are limited in their capacity to differentiate into canonical CD103+/CD69+ TRM CD8+ T cells." (PMID 30875408, 2019). "In some tissues, persistence of viral antigen is thought to influence retention of TRM, while other studies show expression of CD103 and CD69 remain elevated following viral infection in the absence of detectable viral antigen." (PMID 29602245, 2018). "At 48 hours post-infection, we observed that both NK and NKT cells from TLR3KO mice upregulated CD69 to levels comparable with WT NOD mice suggesting that these cells can respond normally to viral infection despite the absence of TLR3 signaling." (PMID 19122812, 2009).
viral infection (continued). "Intra-nasal immunization with N SRS was specifically associated with the presence of CD4+CD69+ lymphocytes as early as 4 days and up to 10 days after virus infection, as compared with non vaccinated or LT(R192G) immunized mice where CD8+CD69+ lymphocytes were the predominant subset." (PMID 18335041, 2008). "CD69 is well recognized as a very early activation marker in human and mouse studies, but its application has not yet been validated in pigs in the setting of viral infections." (PMID 35746813, 2022). "It will be of interest to determine the precise localization (e.g., T cell zones or subcapsular sinus) occupied by CD69+ CD103+ mLN Trm in general and if this distribution is altered for 4M vs 1M Trm as their localization could be important in the control of virus infections entering the mLN." (PMID 34143731, 2021). "Moreover, residence is a dominant feature of CD4+CD69+ memory T cells generated by viral infection in various non-lymphoid tissues." (PMID 32508808, 2020). "In our system, around 90% of CD103+CD69+ OT-1 TIL derived from B16-Ova tumors at day 21 also expressed VLA-1, strongly indicating that VLA-1 is induced as part of the program of TRM differentiation in tumors, similar to previous reports from models of virus infection." (PMID 28018343, 2016). "Thus, CD69 expression corresponds to live virus infection but not necessarily to virus induced cytotoxicity." (PMID 19125202, 2009). "Although anti-porcine CD69 mAbs were generated in this and in another study, whether they are applicable for detecting the early activation of lymphocytes in the setting of viral infection has not yet been proved." (PMID 35746813, 2022). "The CD8+ T cell-specific clonotype, however, was only expressed in T cells that had little expression of CD69, FOS and FOSB, suggesting that this was not an active viral infection." (PMID 38665903, 2023). "Thus, despite residing at a higher activation level as observed above (CD69), DN2 cells do not display an enhancement in BCR signaling with severe viral infection." (PMID 36131937, 2022).